TSSK4 (testis specific serine kinase 4)
Description:
Serine/threonine kinase which is involved in male germ cell development and in mature sperm function (By similarity). May be involved in the Cre/Creb signaling pathway (By similarity). Phosphorylates CREB1 on 'Ser-133' in vitro and can stimulate Cre/Creb pathway in cells. Phosphorylates CREM on 'Ser-116' in vitro (By similarity). Phosphorylates ODF2 on 'Ser-95' (By similarity).
Synonyms: TSK-4; C14orf20; STK22E; TSSK5; TSK4
Tractability: Small molecule: a high-quality ligand is known; it belongs to a druggable protein family. PROTAC: UniProt records ubiquitination sites on it.
Target class: Enzyme; Transferase
Gene: Protein-coding gene on chromosome 14 (24,205,696 to 24,208,362, forward strand). Ensembl gene ENSG00000139908.
Subcellular location: Cytoplasmic vesicle, secretory vesicle, acrosome; Cell projection, cilium, flagellum
Subcellular location (Human Protein Atlas): Cell Junctions
Gene Ontology:
Molecular function: ATP binding; magnesium ion binding; protein binding; protein serine kinase activity; protein serine/threonine kinase activity; identical protein binding; protein homodimerization activity; protein kinase activity; protein-containing complex binding
Biological process: flagellated sperm motility; fertilization; spermatid development
Cellular component: acrosomal vesicle; motile cilium; sperm flagellum
Genetic constraint (gnomAD): Loss-of-function variants: 24 observed, 33.01 expected, observed/expected ratio (o/e) 0.73, 90% interval 0.53 to 1.02. The upper end of that interval is the gene's LOEUF score, 1.02, which puts it in group 4 of 6, group 1 being the genes least tolerant of losing a copy. Missense variants: 329 observed, 437.42 expected, observed/expected ratio (o/e) 0.75, 90% interval 0.69 to 0.82. Synonymous variants: 151 observed, 167.75 expected, observed/expected ratio (o/e) 0.9, 90% interval 0.79 to 1.03.
Homologues: Orthologues: chimpanzee TSSK4 (96% identical), macaque TSSK4 (94% identical), dog TSSK4 (87% identical), pig TSSK4 (87% identical), rabbit TSSK4 (86% identical), mouse Tssk4 (83% identical), rat Tssk4 (75% identical), guinea pig TSSK4 (67% identical), Drosophila melanogaster CG9222 (35% identical), zebrafish nim1kb (26% identical), Caenorhabditis elegans F23C8.8 (23% identical). Paralogues in human: TSSK2 (37% identical), TSSK1B (37% identical), TSSK3 (33% identical), SIK3 (31% identical), NUAK1 (31% identical), SIK1 (31% identical), SIK2 (31% identical), TSSK6 (30% identical), NUAK2 (30% identical), PRKAA2 (30% identical), SNRK (30% identical), PRKAA1 (29% identical), and 5 more.
Diseases named in the same sentence as TSSK4 in open-access papers:
TSSK4 is named in the same sentence as 12 diseases in open-access papers, as found by Europe PMC text mining. Sharing a sentence is not in itself a finding about the gene and the disease. The quoted sentences say what the papers report.
infertile (3 papers, 2022 to 2025). "In 2013, a study found that 5 out of 372 infertile Chinese men who had oligospermia or azoospermia contained some mutation in the Tssk4 gene." (PMID 40305308, 2025). "Mutation in the TSSK4 gene was also found to be harmful to spermatogenesis in infertile Chinese men." (PMID 36185367, 2022). "For instance, small-molecule activators of TSSK4 could ameliorate motility defects, while anti-phospho-Gudu antibodies may serve as biomarkers for infertility diagnosis." (PMID 40335644, 2025).
Azoospermia (2 papers, 2023 to 2025). Absence of any measurable level of sperm,whereby spermatozoa cannot be observed even after centrifugation of the semen pellet. "Indeed, single-nucleotide mutations of TSSK2, TSSK4, and TSSK6 are reportedly associated with azoospermia and severe oligospermia." (PMID 37149634, 2023).
fibrosis (1 paper, 2021). the formation of excess fibrous connective tissue in an organ or tissue in a reparative or reactive process. "The same results further presented that BAD translocated to mitochondria in lung tissues of bleomycin-induced fibrosis, which was dramatically suppressed in lentivirus-mediated TSSK4-deficient model mice." (PMID 34645797, 2021).
Insulin resistance (1 paper, 2018). Increased resistance towards insulin, that is, diminished effectiveness of insulin in reducing blood glucose levels. "TSSK4 appears to have a rather specialized role for male fertility while sequence variants in ATP10D have been demonstrated to significantly associate with metabolic disorders including insulin resistance." (PMID 29351342, 2018).
lung fibrosis (1 paper, 2021). "Taken together, in fibrotic lung tissue, TSSK4 is selectively upregulated in AT-II cells, thereby promoting the loss of AT II and pathological progress of pulmonary fibrosis." (PMID 34645797, 2021). "Taken together, TSSK4 upregulation in AT-II cells plays an important role in TNF-α-induced cellular apoptosis in vitro and AT-II loss in pulmonary fibrosis." (PMID 34645797, 2021). "In this article, based on high-throughput proteomic analysis, we report that TSSK4 is selectively expressed in AT II and promotes AT-II loss through HSP–AKT signaling axis during pulmonary fibrosis." (PMID 34645797, 2021). "It is one of the molecular mechanisms for the process of pulmonary fibrosis, in which interfering the expressing of TSSK4 or regulating the activity of AKT could be the potential therapeutic strategies to improve pathological process of IPF." (PMID 34645797, 2021). "Our findings highlight the importance of TSSK4 in regulating pulmonary fibrosis by facilitating AT-II loss through HSP90-AKT signaling, all of which suggest TSSK4 and the regulating mechanism as attractive targets for the clinical intervention of pulmonary injury and fibrosis." (PMID 34645797, 2021). "Taken together, given the importance of TSSK4 upregulation in AT II for cellular apoptosis and thereby fibrosis, our finding is likely to have great significance for further understanding the pathogenesis of pulmonary fibrosis and subsequent clinical application of IPF." (PMID 34645797, 2021).
TSSK4 also shares sentences with these, for which no sentence is quoted: infection (2 papers); emphysema (1); lung disease (1); male infertility (1); metabolic disorders (1); oligospermia (1); testicular embryonic carcinoma (1).